HBB (hemoglobin subunit beta)
Diseases named in the same sentence as HBB in open-access papers (continued):
Sharing a sentence is not in itself a finding about the gene and the disease.
genetic disorder (20 papers, 2005 to 2025). "SCD is an autosomal recessive genetic disorder characterized by a mutation in the beta‐globin gene (HBB), where a single nucleotide substitution (adenine to thymine) in codon 6 results in the replacement of glutamic acid with valine." (PMID 40152112, 2025). "Sickle cell disease (SCD) is a prevalent genetic disorder characterized by mutations in the HBB gene responsible for the beta-globin chain formation." (PMID 39156342, 2024). "β-Thalassemias represent a group of genetic disorders caused by human hemoglobin beta (HBB) gene mutations." (PMID 32912325, 2020). "β-thalassemia, caused by mutations in the human hemoglobin β (HBB) gene, is one of the most common genetic diseases in the world." (PMID 33193694, 2020). "Sickle cell disease (SCD) is a set of genetic disorders caused by mutations in the HBB gene, which encodes the beta-globin chain of hemoglobin." (PMID 32854639, 2020). "In human beings, one of the most common genetic diseases is β-thalassemia that is caused by mutation in human hemoglobin beta (HBB) gene." (PMID 27725818, 2016). "These are genetic disorders caused by mutations in the beta globin (HBB) gene." (PMID 37908590, 2023). "Beta-Thalassemia is a genetic disorder caused by a mutation inside the beta-hemoglobin (HBB) gene." (PMID 21767363, 2011).
infection (7 papers, 2011 to 2025). The state of being infected such as from the introduction of a foreign agent such as serum, vaccine, antigenic substance or organism. "Meanwhile, we observed that certain biomarkers (SLC7A5, PDE4D, CXCR4, PER1, PIK3R1, HBA1, HBB) were elevated during the pre-infection phase (LTBI), while others (SOCS3, GZMK, HIS1H3B) were upregulated in the post-infection phase (ATB)." (PMID 40589756, 2025). "Additionally, the detection of proteins with peptidase regulatory and antioxidant activities, such as GPx and HBB, points to compensatory mechanisms activated in response to oxidative stress and inflammation during infection." (PMID 41156653, 2025). "Hemoglobin subunit beta showed an interaction of broiler genetic line×coccidia infection." (PMID 21297942, 2011). "As a further control for shRNA target specificity, infection of prostate LNCaP cells, which lack endogenous HBB expression, does not affect cell proliferation." (PMID 28181495, 2017).
autosomal recessive disease (2 papers, 2022 to 2023). Autosomal recessive form of disease. "β-thalassemias is one of the most common autosomal recessive inherited disorders in the world and is caused by more than 300 mutations of the HBB gene and characterized by a quantitative deficiency of β-globin chains." (PMID 39872888, 2023). "β-thalassemia is an autosomal recessive disease with the reduction or absence in the production of β-globin chain, which is caused by mutations in the HBB gene." (PMID 36476827, 2022). "β-thalassemia is an autosomal recessive disease with the reduction or absence in the production of β-globin chain in the hemoglobin, which is caused by mutations in the Hemoglobin subunit beta (HBB) gene." (PMID 36476827, 2022).
cardiovascular disease (2 papers, 2013 to 2016). "For example, the ADIPOQ, AMY1A, CFB, HP and HBB are associated with the metabolic diseases, while the FBP4, HP, LPL and MYL2 are related to the cardiovascular diseases." (PMID 24204599, 2013).
infectious disease (2 papers, 2016 to 2025). A disorder directly resulting from the presence and activity of a microbial, viral, or parasitic agent in humans.
kidney disease (2 papers, 2023). "Other studies have indicated that HBB, HSPA6, and NFKBIZ may play essential roles in kidney disease." (PMID 37293297, 2023).
retinal disorder (2 papers, 2023 to 2025). Any disease or disorder of the retina. "Moreover, ophthalmic presentations of DFO‐related retinopathy are mostly associated with transfusion‐dependent thalassemia due to mutated β‐hemoglobin, which is encoded by hemoglobin subunit β (HBB)." (PMID 36645044, 2023).
HBB also shares sentences with these, for which no sentence is quoted: Diabetes (4 papers); heart failure (4); Autoimmunity (3); beta-thalassemia major (3); hemochromatosis (3); parasitemia (3); phenylketonuria (3); African trypanosomiasis (2); Alpha-thalassemia (2); autosomal recessive deafness (2); Hypertension (2); metabolic disease (2); Parkinson's (2); red blood cell disorders (2); vasculopathy (2); 21-hydroxylase deficiency (1); achondroplasia (1); Alzheimer disease (1); bacterial infection (1); biotinidase deficiency (1); bone marrow failure (1); cataract (1); cholera (1); chronic granulomatous disease (1); chronic lung disease (1); chronic myeloid leukemia (1); Cognitive impairment (1); Cohen syndrome (1); colorectal cancer (1); congenital neutropenia (1).
A further 69 diseases each share a sentence with HBB in 1 paper.